FTO (FTO alpha-ketoglutarate dependent dioxygenase)
Diseases named in the same sentence as FTO in open-access papers (continued):
Sharing a sentence is not in itself a finding about the gene and the disease.
metabolic syndrome (71 papers, 2008 to 2025). A cluster of metabolic risk factors for CARDIOVASCULAR DISEASES and TYPE 2 DIABETES MELLITUS. "For MDD and metabolic syndrome, we identified four genomic regions containing a causal variant for both traits shared by both sexes, which also mapped to the FTO gene." (PMID 40858613, 2025). "The aim of this study was to examine the association between the FTO rs9939609 polymorphism and the rate of fat oxidation during exercise, as well as its relationship with metabolic syndrome criteria in healthy participants." (PMID 39858551, 2024). "The aim of this study was to analyze the association between the FTO rs9939609 polymorphism with the rate of fat oxidation during exercise and metabolic syndrome criteria in healthy participants." (PMID 39858551, 2024). "Patients with T2DM or dyslipidemia had a higher frequency of AA, AT or AA + AT genotypes as well as A allele of FTO rs9939609 polymorphism than those free of T2DM or dyslipidemia (P ≤ 0.04 for all)." (PMID 38161971, 2023). "Patients with T2DM or dyslipidemia had a higher frequency of GG, GT or GG + GT genotypes as well as G allele of FTO rs17817449 polymorphism than those free of T2DM or dyslipidemia (P ≤ 0.03 for all)." (PMID 38161971, 2023). "The present study demonstrates that FTO rs9939609 and rs17817449 polymorphisms are significantly and independently associated with the susceptibility to dyslipidemia and T2DM in a Chinese Han population." (PMID 38161971, 2023). "FTO is a feeding-signal-associated gene, influencing an individual’s overall food intake and energy homeostasis, contributing to the etiology of metabolic syndrome, a risk factor for CVD, when coupled with poor diet and lifestyle behaviors." (PMID 37702886, 2023). "After 12 weeks of hydroalcoholic extract of arti-choke supplement in women with metabolic syndrome, those with risk allele of FTO showed better improvement in serum TG levels than those without risk allele." (PMID 36185685, 2022). "FTO rs9939609 and increase risk in metabolic syndrome component risk factors by race over time in the ARIC study." (PMID 32028392, 2020). "The present study was aimed to investigate the association of ACE (rs4646994), FABP2 (rs1799883), MTHFR (rs1801133) and FTO (rs9939609) genes polymorphism in T2DM with dyslipidemia." (PMID 28890888, 2017). "The FTO rs9939609 SNP was associated with an increased risk for Metabolic Syndrome in type 2 diabetic populations at a tertiary care unit of Karachi, Pakistan." (PMID 25878631, 2015). "The aim of the study was to see the association of SNP in FTO gene, rs9939609, with metabolic syndrome at a tertiary care unit of Karachi, Pakistan." (PMID 25878631, 2015). "Recent studies have identified that several genetic loci traditionally associated with T2D, such as TCF7L2, IGF2BP2, and FTO, may also influence IR in individuals with T1D, particularly in those with a long disease course or features of metabolic syndrome." (PMID 41019343, 2025). "Genetic studies have further revealed that polymorphisms in the FTO gene are associated with increased susceptibility to metabolic syndrome and may contribute to the pathogenesis of schizophrenia, thereby offering a possible predictive marker for the disorder." (PMID 40590504, 2025). "Such as, it has been shown that SNP rs34269950 in the RRACH genome, located in the 3′UTR of RUNX1T1, is significantly regulated by FTO in rural populations in the Caucasus region of Australia, providing important clinical evidence for the association of m6A with metabolic syndrome." (PMID 38562618, 2024). "The metabolic and physiological responses to the FTO rs9939609 polymorphism observed in this healthy cohort may differ significantly from those in populations with existing metabolic syndrome or other health conditions." (PMID 39858551, 2024). "Polymorphisms of the FTO gene have been linked to depression and metabolic syndromes." (PMID 38384936, 2024).
metabolic syndrome (continued). "Consequently, the objective of this study was to investigate the association between the rs9939609 in FTO gene and metabolic syndrome and to evaluate the components of metabolic syndrome in this same Chilean child population." (PMID 34208143, 2021). "They concluded that FTO polymorphism has a relationship with metabolic syndrome (OR = 1.17)." (PMID 31200723, 2019). "FTO has been correlated with metabolic syndrome and diabetes risk." (PMID 28859657, 2017). "In addition our study, by linking FTO polymorphism with metabolic syndrome highlights the possible link between the FTO polymorphism with cardiovascular disorders." (PMID 28915859, 2017). "Therefore, this study was designed to investigate the association of FTO gene rs9939609 with metabolic syndrome and its endophenotypes in Arab female population from Egypt." (PMID 28915859, 2017). "This study was designed to investigate FTO rs9939609 association with metabolic syndrome (MetS) as well as biochemical parameters as plasma glucose, serum triacylglycerol (TAG), total cholesterol (TC) and transaminases enzymes in Arab female population from Egypt." (PMID 28915859, 2017). "Recently, several studies have addressed whether FTO in humans might be associated with the metabolic syndrome." (PMID 25144618, 2014). "Also the discovery of the fat mass and obesity-associated protein (FTO) gene showed the genetic role in the development of obesity and metabolic syndrome (MetS)." (PMID 24999296, 2014). "In this study, we could show that FTO is a factor which contributes substantially to the development of the obese phenotype in leptin-deficient mice and thus to the metabolic syndrome as exemplified by hyperglycaemia and increased lipid content in liver." (PMID 25144618, 2014). "The present study shows for first time that FTO gene rs9939609 is genetic risk factor for metabolic syndrome in Egyptian population which may help in understanding the biology of this complex syndrome and highlighted that this association may be through HDL-C component." (PMID 28915859, 2017). "Therefore, replacing the traditional diet with contemporary hepatopathogenic foods, coupled with the presence of risk alleles, including the FTO rs9939609 polymorphism, could contribute to the higher susceptibility for dyslipidemias, IR, and HGL among the Mexican population." (PMID 41141248, 2025). "Notably, two FTO variants (rs9939609 and rs8050136) achieved independent significance, suggesting that genetic predisposition may act synergistically with biochemical parameters in modulating dyslipidemia risk." (PMID 41303403, 2025). "FTO promoter methylation has been analyzed in pathologies such as metabolic syndrome, where increased levels of DNA methylation were found compared to participants without any metabolic conditions." (PMID 39040764, 2024). "In line with our findings, a series of studies have reported significant correlations of FTO rs9939609 and rs17817449 polymorphisms with the risk of T2DM and dyslipidemia." (PMID 38161971, 2023). "Multivariate logistic regression analysis between the FTO rs9939609 and rs17817449 polymorphisms and T2DM as well as dyslipidemia." (PMID 38161971, 2023). "Relations between FTO polymorphisms and T2DM as well as dyslipidemia are possibly mediated by abnormal glucolipid metabolism and increased energy intake." (PMID 38161971, 2023). "Minor alleles of FTO rs9939609 and rs17817449 polymorphisms confer a higher risk of T2DM and dyslipidemia, and the risk is further increased among obese individuals." (PMID 38161971, 2023). "Multivariate logistic regression analyses showed that FTO rs9939609 and rs17817449 polymorphisms were independently associated with T2DM as well as dyslipidemia after adjustment for age, sex, smoking and other metabolic diseases." (PMID 38161971, 2023). "Overexpression of FTO results in increased lipid accumulation in liver and muscle cells and reduces atherogenic dyslipidemia." (PMID 36894991, 2023).
metabolic syndrome (continued). "Hypermethylation of FTO, hypermethylation of PPARγ, and hypomethylation PDK4 associated with metabolic syndrome, T2D and both metabolic syndrome and T2D, respectively." (PMID 30564199, 2018). "To determine the relevance of FTO for the development of the metabolic syndrome we analysed different parameters in combined homozygous deficient mice (Lepob/ob;Fto−/−)." (PMID 25144618, 2014). "Taken together, these findings demonstrate that rs9939609 and rs8050136 in the FTO gene are robustly associated with dyslipidemia in perimenopausal women, while rs9940128 appears not to exert a major independent effect." (PMID 41303403, 2025). "Analysis of FTO polymorphisms revealed that rs9939609 and rs8050136 were significantly associated with dyslipidemia, whereas rs9940128 showed no independent effect." (PMID 41303403, 2025). "Collectively, these results demonstrate that lipid-related markers retain their central role as predictors of dyslipidemia, while the addition of FTO variants modestly enhances the explanatory power without altering the dominance of biochemical determinants." (PMID 41303403, 2025). "Among the carriers of GG or GT genotype of the FTO rs17817449 polymorphism, the prevalence of dyslipidemia in obese patients was higher than that in non-obese subjects (P < 0.01)." (PMID 38161971, 2023). "Obese or T2DM carriers of the AA or AT genotype of the FTO rs9939609 polymorphism had a higher prevalence of dyslipidemia compared to non-obese or non-T2DM carriers of the AA or AT genotype (P = 0.03 for both)." (PMID 38161971, 2023). "In addition, lowering and inhibiting ROS1 kinase, FTO protein, and lipase can reduce the incidence of metabolic syndrome in obese people, and inhibiting these receptors can also be an anti-aging approach." (PMID 37764670, 2023). "FTO rs9939609 and longitudinal changes in metabolic syndrome by race over time in the ARIC study." (PMID 32028392, 2020). "Blood lipids are not influenced by the FTO rs9939609 polymorphism, suggesting the FTO-dyslipidemia link is mediated by adiposity and weight management is important in preventing FTO-related lipid variations." (PMID 33348678, 2020). "Significant association of FTO AA genotype was observed in T2DM cases without dyslipidemia compared to the controls (P<0.001)." (PMID 28890888, 2017). "In conclusion ACE, FABP2, FTO and MTHFR genes were found to be associated with T2DM, and additionally ACE and MTHFR genes might be implicated with the development of dyslipidemia in T2DM cases." (PMID 28890888, 2017). "A significant association of FTO AA genotype was observed in T2DM cases without dyslipidemia compared to the controls (P<0.001)." (PMID 28890888, 2017). "As FTO has a function in energy homeostasis we were interested to see whether FTO is also important for the development of the metabolic syndrome." (PMID 25144618, 2014). "Additionally, it is unclear whether FTO influences metabolic syndrome (MetS) through mechanisms other than BMI’s impact." (PMID 38892547, 2024). "The aim of the study was to examine the expression profile of genes (APOE, FTO, and LPL) associated with metabolic syndrome (MetS) in subjects with concomitant atrial fibrillation (AF)." (PMID 39166676, 2024). "Moreover, a significant association of FTO variant was found in Indian patients with T2DM without dyslipidemia." (PMID 30170548, 2018). "However, when analyzed separated, neither MC4R nor FTO were associated with any individual metabolic syndrome feature, including waist circumference." (PMID 23849767, 2013). "However, as waist circumference was not reported in this study, it remains unclear whether genetic variation of FTO play also an important role in the development of the metabolic syndrome." (PMID 18799002, 2008). "However, we did not analyze whether the risk of metabolic syndrome is modified with this variant of the FTO gene in this sample." (PMID 34208143, 2021).
metabolic syndrome (continued). "Concerning the association of metabolic syndrome with polymorphisms of the FTO gene, a meta-analysis concluded that the FTO gene might play a critical role in leading to MetS." (PMID 34208143, 2021). "The mechanisms underlying the correlations between FTO rs9939609 and rs17817449 polymorphisms and T2DM as well as dyslipidemia have not been fully elucidated." (PMID 38161971, 2023). "The frequency of FTO TT genotype was 18.9% in T2DM cases without dyslipidemia which is significantly lower in comparison with Chinese T2DM cases (45%)." (PMID 28890888, 2017). "The frequency of FTO AT genotype was 71.5% in T2DM cases without dyslipidemia which is significantly higher in comparison with Chinese (47.6%) and American (47.3%) populations." (PMID 28890888, 2017). "The additional risk associated with possessing several SNPs, particularly when integrating FTO, MC4R, and FABP2, increases the likelihood of developing metabolic syndrome, even in the absence of observable symptoms." (PMID 41226372, 2025). "It appeared that the effect sizes of most T2D-associated SNPs, with the exception of a few outliers (e.g., FTO, MC4R, POCS, and TFAP2B), were not affected by BMI or dyslipidemia." (PMID 30054458, 2018). "This is the first study to report a negative correlation between the expression of the FTO gene and FBG, as well as the expression of the LPL gene, and a positive correlation between the expression of the FTO gene and cardiac troponin 1 in AF subjects with metabolic syndrome." (PMID 39166676, 2024).
Insulin resistance (69 papers, 2010 to 2026). Increased resistance towards insulin, that is, diminished effectiveness of insulin in reducing blood glucose levels. "Many factors contribute to the development of brain insulin resistance, one of which is genetic polymorphism in the Fat Mass and Obesity-Associated Protein (FTO) gene." (PMID 38255204, 2024). "A Go-DARTS study on 4897 diabetic patients concluded that the AA genotype of the FTO gene variant rs9939609 had a remarkable association with increased BMI, atherogenic lipid profile, and insulin resistance." (PMID 39257882, 2024). "Further studies have shown that endothelial FTO deficiency can protect mice against high-fat diet–induced glucose intolerance and insulin resistance by enhancing AKT phosphorylation." (PMID 37781923, 2023). "The FTO gene was also considerably more expressed in obese children and patients with established insulin resistance and was linked to an increase in WC, body fat, and a higher fasting free fatty acid concentration." (PMID 34912641, 2021). "The aim of this study was to determine the association between omentin Val109Asp and FTO rs9939609 polymorphisms and insulin resistance in newly-diagnosed T2D patients." (PMID 31200723, 2019). "This emphasizes the necessity to perform a multicenter study with a larger sample size to clarify the impact of FTO rs9939609 variant on insulin resistance in obese female adolescent in Indonesia." (PMID 29764479, 2018). "FTO rs9939609 variant has been shown to be associated with insulin resistance in Caucasian children." (PMID 29764479, 2018). "There are several established findings regarding the association between insulin resistance and FTO rs9939609." (PMID 29764479, 2018). "They found association between the FTO rs8050136 SNP and cerebrocortical insulin resistance in humans, but this polymorphism is in linkage disequilibrium with rs9939609 (rs9939609, D′ = 0.9998); so we cannot rule out a causal effect of the rs9939609 SNP." (PMID 29854435, 2018). "We investigated the association between FTO rs9939609 polymorphisms and insulin resistance in obese female adolescents in Indonesia, a genetically distinct group within Asia." (PMID 29764479, 2018). "In this study, we were unable to show any significant association between FTO rs9939609 common variant and insulin resistance." (PMID 29764479, 2018). "The association between the FTO rs9939609 variants (TT, TA, AA) and insulin resistance was determined by Chi square test." (PMID 29764479, 2018). "At variance with previous studies, in our population FTO gene polymorphisms were associated only with an increased BMI, but not with metabolic parameters such as lipids, impaired glucose tolerance, or insulin resistance." (PMID 22454631, 2012). "In the current study, the association between a common variant in the FTO gene and adiposity and insulin resistance-related phenotypes was investigated in 1978 EA and AA youths, available from the Georgia Cardiovascular Twin, LACHY and APEX studies." (PMID 20377915, 2010). "This study aimed to assess the influence of FTO variant rs9939609 on adiposity, insulin resistance, energy intake and physical activity in European - (EA) and African-American (AA) youth." (PMID 20377915, 2010). "Insulin and insulin resistance levels were greater in patients with the three FTO polymorphisms." (PMID 38674326, 2024). "These genetic variations may potentially impact FTO expression or enzyme activity, resulting in metabolic alterations that disrupt glucose metabolism and induce insulin resistance, consequently heightening the susceptibility to GDM." (PMID 39659616, 2024). "Moreover, there are evidences suggesting that certain variants of the FTO gene are associated with insulin resistance and higher inflammatory response." (PMID 37697388, 2023).